ATRNL1 (attractin like 1)
Description:
May play a role in melanocortin signaling pathways that regulate energy homeostasis.
Synonyms: KIAA0534; FLJ45344; ALP; bA338L11.1; bA454H24.1
Tractability: Antibody: UniProt predicts a signal peptide or a membrane-spanning region. PROTAC: its protein half-life has been measured.
Gene: Protein-coding gene on chromosome 10 (115,093,365 to 115,948,999, forward strand). Ensembl gene ENSG00000107518.
Subcellular location: Membrane
Subcellular location (Human Protein Atlas): Mitochondria; Nucleoplasm
Gene Ontology:
Molecular function: protein binding; Notch binding
Cellular component: membrane
Genetic constraint (gnomAD): Loss-of-function variants: 37 observed, 90.49 expected, observed/expected ratio (o/e) 0.41, 90% interval 0.31 to 0.54. The upper end of that interval is the gene's LOEUF score, 0.54, which puts it in group 2 of 6, group 1 being the genes least tolerant of losing a copy. Missense variants: 920 observed, 1,068.9 expected, observed/expected ratio (o/e) 0.86, 90% interval 0.81 to 0.91. Synonymous variants: 386 observed, 372.79 expected, observed/expected ratio (o/e) 1.04, 90% interval 0.95 to 1.13.
Homologues: Orthologues: chimpanzee ATRNL1 (99% identical), macaque ATRNL1 (99% identical), dog ATRNL1 (98% identical), mouse Atrnl1 (96% identical), pig ATRNL1 (95% identical), rat Atrnl1 (95% identical), rabbit ATRNL1 (94% identical), tropical clawed frog atrnl1 (80% identical), zebrafish atrnl1b (74% identical), zebrafish atrnl1a (70% identical). Paralogues in human: ATRN (60% identical), MEGF8 (27% identical), LAMA5 (17% identical), LAMA2 (16% identical), LAMA1 (16% identical), LAMA3 (16% identical), LAMB4 (15% identical), LAMB1 (14% identical), LAMB2 (14% identical), LAMC3 (13% identical), AGRN (13% identical), USH2A (13% identical), and 15 more.
Diseases named in the same sentence as ATRNL1 in open-access papers:
ATRNL1 is named in the same sentence as 20 diseases in open-access papers, as found by Europe PMC text mining. Sharing a sentence is not in itself a finding about the gene and the disease. The quoted sentences say what the papers report.
adenoma (1 paper, 2016). A neoplasm arising from the epithelium. "Two adenomas were found to carry truncating mutations in the attractin‐like 1 (ATRNL1) gene." (PMID 26414517, 2016).
brain cancer (1 paper, 2025). A primary or metastatic malignant neoplasm affecting the brain. "However, the symptoms associated with ATRNL1 and spinocerebellar ataxia are classified as chromosomal genetic disorders, which theoretically do not have a substantial relationship with brain cancer." (PMID 40608007, 2025).
osteoarthritis (1 paper, 2023). A noninflammatory degenerative joint disease occurring chiefly in older persons, characterized by degeneration of the articular cartilage, hypertrophy of bone at the margins and changes in the synovial membrane. "The ATRNL1 gene, which was identified in this study, can regulate the expression of SOX9 and is significantly highly expressed in the cartilage tissues of patients with osteoarthritis." (PMID 37667381, 2023).
Solid Pseudopapillary Neoplasm of the Pancreas (1 paper, 2023). A low-grade malignant neoplasm that arises from the exocrine pancreas. "A retrospective study of 454 cases with solid pseudopapillary neoplasm of the pancreas uncovered that ATRNL1 is one of the top three frequently mutated genes." (PMID 37752559, 2023).
spinocerebellar ataxia (1 paper, 2025). "Attractin like 1 (ATRNL1) is widely acknowledged for its role in the process of cell migration, with associated disorders including spinocerebellar ataxia." (PMID 40608007, 2025).
cancer (2 papers, 2018 to 2020). A tumor composed of atypical neoplastic, often pleomorphic cells that invade other tissues. "TUSC3 and ATRNL1 were predominantly methylated in cancer cell lines derived from the digestive system, such as stomach, pancreas and biliary tract, although their hypermethylation was also very common in hematological malignancies." (PMID 30018746, 2018). "Seven genes had variants found in the cancers of at least two ‘poor’ responders but in no 'good’ responders: ATRNL1, BAIAP2L2, ZNF384, ST6GALNAC5, ENSCAFG00000030179 (human ortholog: riboflavin kinase RFK), ENSCAFG00000029320, and ENSCAFG00000007370 (human ortholog: immunoglobin IGKV4-1)." (PMID 32857815, 2020). "Data mining for 5′-end CpG island methylation of TUSC3, ATRNL1, POMT1 and SAMD4A in cancer cell lines and primary tumors showed that the epigenetic defect was commonly observed among different tumor types in association with the diminished expression of the corresponding transcript." (PMID 30018746, 2018). "The occurrence of TUSC3, ATRNL1, POMT1 or SAMD4A promoter CpG island hypermethylation was not a restricted in vitro phenomenon of long-cultured cancer cell lines." (PMID 30018746, 2018).
ATRNL1 also shares sentences with these, for which no sentence is quoted: Alzheimer disease (1 paper); atrial fibrillation (1); autism (1); breast carcinoma (1); Cognitive impairment (1); colon adenocarcinoma (1); colorectal cancer (1); Esophageal Carcinoma (1); Head-Neck Squamous Cell Carcinoma (1); hematological malignancies (1); hypertrophic cardiomyopathy (1); rectum adenocarcinoma (1); scoliosis (1); tumor (1).